GCNT1 (glucosaminyl (N-acetyl) transferase 1)
Diseases named in the same sentence as GCNT1 in open-access papers (continued):
Sharing a sentence is not in itself a finding about the gene and the disease.
tumor (19 papers, 2009 to 2025). "According to multivariate analysis, PSA levels, margin status, and GCNT1 expression in the tumor were independent risk factors for PSA recurrence." (PMID 26390303, 2015). "We previously reported that branched glycans formed by GCNT1 regulate the NK cell–tumor cell interactions." (PMID 40149658, 2025). "Consistent with this, knockdown of GCNT1 using sub-cutaneous in vivo mouse models significantly reduces the growth of CWR22RV1 tumours, whereas overexpression of GCNT1 significantly increases the growth of PC3 tumours." (PMID 37813880, 2023). "Indeed, using an intra-cardiac injection model, we find that upregulation of GCNT1 in PC3 cells significantly reduces the number of metastatic tumours formed (p = 0.0295)." (PMID 37813880, 2023). "GCNT1-positive tumor showed significantly higher Gleason score and larger tumor volume." (PMID 26390303, 2015). "At the cellular level, USP18, TLR7, IL21R, GCNT1 and CHST7 were expressed in various tumor cell lines, while the expression of LHX2, IL2RA and IL5RA was low in CCLE." (PMID 34001679, 2021). "Over 80% of tumor specimens with extracapsular extension of PCa (pT3 and pT4) expressed GCNT1, and GCNT1-positive tumors were significantly larger than GCNT1-negative tumors." (PMID 26390303, 2015). "In PNAdneg TEC from I.P. tumors grown in TNFR1/2-/- mice, there was no reduction in the expression of genes encoding scaffolding proteins or most glycosyl transferases, although the expression of Gcnt1 increased." (PMID 36189308, 2022).
cancer (16 papers, 2009 to 2025). A tumor composed of atypical neoplastic, often pleomorphic cells that invade other tissues. "Our findings suggest increased GCNT1 expression correlates with upregulation of the cancer-associated sLeX glycan on the cell surface, which is a functional ligand for Selectins43–45." (PMID 37813880, 2023). "Core2 β-1,6-N-acetylglucosaminyltransferase-1 (GCNT1) is an enzyme that plays a key role in the formation of core 2-branched O-glycans, and GCNT1 expression is associated with the progression of several types of cancer." (PMID 27730440, 2017). "GCNT1 is important for formation of core 2 branched O-glycans and has been implicated in synthesis of the cancer-associated Sialyl Lewis X (SLeX) antigen." (PMID 27428423, 2016). "Some glycosylation enzymes (GALNT7, GCNT1, TAP1, PGM3, etc.)are under the control of AR and link to the synthesis of cancer-associated glycans such as sialyl-Tn (sTn), sialyl LewisX (SleX)." (PMID 35853851, 2022). "It has also been reported that GCNT1-expressing cancers can escape the host immune response, especially from host natural killer cells that bind to galectin-3 on core 2-branching O-glycans." (PMID 26390303, 2015). "Although the mechanism of GCNT1-driven regulation in cancer progression is poorly understood, our study demonstrates that GCNT1 can be a predictor of the malignant potential of PCa." (PMID 26390303, 2015). "GCNT1 is one of the glycosyltransferases that forms the core 2 O-glycans on the surface of lymphocytes and various cancer cells." (PMID 26390303, 2015). "A review of the literature revealed that aberrant expression of CKMT1A, GCNT1, NCALD, NFKBIB, NOMO3/Nodal, SLC16A5, or TRPV2 was correlated with cancer." (PMID 31363162, 2019). "Because GCNT1 is not a cancer-specific protein, its expression was unsuitable for PCa screening." (PMID 26390303, 2015).
infection (5 papers, 2014 to 2023). The state of being infected such as from the introduction of a foreign agent such as serum, vaccine, antigenic substance or organism. "The increased susceptibility of GCNT1 deficient mice to infection was largely driven by exacerbated neutrophil counts, which led to lung lesions, inflammation, and other pathologic features in the lungs of affected mice." (PMID 36793728, 2023). "That, together with our observation that Gcnt1 transcription is upregulated upon infection, led us to question the impact of Gcnt1 deficiency on the expression profile of Lewis antigens in the lung epithelium in naïve or M. tuberculosis infected mice." (PMID 33406734, 2021). "Uninfected Gcnt1 deficient mice presented bone marrow, blood and lung neutrophilia, which further increased with infection." (PMID 32203062, 2020). "Although the transcription of these chemokines in lungs of C57BL/6 or Gcnt1−/− mice was similar upon a low dose of infection, the expression of Cxcl2 was higher in Gcnt1−/− deficient mice than in C57BL/6 upon a high dose of infection." (PMID 32203062, 2020). "Whereas 80% (n = 4) of isotype control-treated Gcnt1−/− mice died between 25–35 days post-infection, only 20% (n = 1) of those treated with the Ly6G depleting antibody did not survive and all C57BL/6 mice survived infection." (PMID 32203062, 2020). "As compared to C57BL/6, Gcnt1−/− mice infected with low doses of Mtb showed increased lung pathology, which was mostly pronounced on day 60 post-infection with increased scores for perivascular and peribronchial lymphocytes." (PMID 32203062, 2020). "Although neutrophils were present in both mouse strains upon infection, these cells accumulated in the case of infected Gcnt1−/− mice, in line with the cytometry data." (PMID 32203062, 2020). "An accumulation of neutrophils in the areas of lesion was particularly observed in infections with high doses of Mtb, being more exacerbated in Gcnt1−/− mice." (PMID 32203062, 2020). "Gcnt1−/− mice, which survived the low dose of infection, showed a higher lung bacterial burden than C57BL/6, particularly on day 60 post-infection." (PMID 32203062, 2020). "Upon a low dose infection, 18.7% of Gcnt1−/− mice succumbed around 30 days post-infection, whereas, as expected, all C57BL/6 mice survived." (PMID 32203062, 2020). "To investigate the mechanisms underlying the increased susceptibility of Gcnt1−/− mice to Mtb, we compared the dynamics of the immune response in C57BL/6 or Gcnt1−/− mice during infection with low or high doses of bacteria." (PMID 32203062, 2020). "Infection of Gcnt1-/- animals with M. tuberculosis strain HN878 resulted on increased SLeX expression on the lung epithelia during the course of infection, as demonstrated by the automatic quantification of staining, which was more pronounced at day 30 and 90 post-infection." (PMID 33406734, 2021). "Except for the Fut4 that was not significantly altered in the Gcnt1 deficient animals, an up-regulation of the α1,3-fucosyltransferases, Fut7, 9, 10 and 11, was observed upon infection by M. tuberculosis, in line with the data obtained for C57BL/6 mice." (PMID 33406734, 2021). "The dynamics of recruitment of myeloid and lymphoid cells to the lung was identical in Gcnt1−/− and C57BL/6 mice infected with a low dose of bacteria, but 30 days after infection all tested immune cell populations were significantly higher in the lung of Gcnt1−/− as compared to C57BL/6 mice." (PMID 32203062, 2020). "Moreover, increased numbers of lung neutrophils were detected in Gcnt1−/− mice, independently of the infection." (PMID 32203062, 2020). "Interestingly, in line with what we had observed in Gcnt1−/− infected mice, the expression of Cxcl2 upon infection was exclusively increased in Gcnt1−/−→Gcnt1−/− chimeric mice." (PMID 32203062, 2020).
infection (continued). "To test the hypothesis of a Gcnt3 compensatory activity in Gcnt1 null mice, we evaluated the transcription levels of Gcnt3, upon infection but no significant changes were found when comparing WT and Gcnt1-/- mice (data not shown)." (PMID 33406734, 2021). "We observed that Gcnt1 deficiency did not change the Lewis antigens lung repertoire, and that Gcnt1-/- mice lung epithelium also displayed increased SLeX, supported by up-regulation of terminal α2,3-sialyl- and α1,3-fucosyl-transferases, in response to infection." (PMID 33406734, 2021).
GCNT1 also shares sentences with these, for which no sentence is quoted: colon carcinoma (5 papers); bladder cancer (3); melanoma (3); cardiovascular disease (2); colorectal adenocarcinoma (2); hepatic carcinoma (2); lung (2); adenocarcinoma (1); asthma (1); autism spectrum disorder (1); benign prostate hyperplasia (1); Cirrhosis (1); depression (1); endometrial carcinoma (1); esophageal cancer (1); gastric cancer (1); glioma (1); helminth infection (1); immune deficiency (1); meningioma (1); metastatic prostate carcinoma (1); oral cavity carcinoma (1); Streptococcus pneumonia infection (1); testicular germ cell tumor (1); urinary system tumors (1); uterine corpus endometrial carcinoma (1); viral myocarditis (1).